TFAM (transcription factor A, mitochondrial)
Diseases named in the same sentence as TFAM in open-access papers (continued):
Sharing a sentence is not in itself a finding about the gene and the disease.
tumor (continued). "Since we proved that COX-2 and p38 positively regulates DRP1/TFAM expression in irradiated tumor cells, we subsequently checked the contribution of COX-2 to p38 phosphorylation." (PMID 30862036, 2019). "We found that attenuated TFAM expression retarded tumour cells proliferation through inducing G1/S phase arrest." (PMID 31062473, 2019). "To detect the function of TFAM on tumour cell proliferation, we established cell lines with low level expression of TFAM by transfecting shRNA plasmids in U‐2 OS, MCF7 and Hep G2 cells." (PMID 31062473, 2019). "Cell proliferation assay showed that down‐regulation of TFAM inhibited the proliferation of the three tumour cell lines." (PMID 31062473, 2019). "Enhanced accumulation of G1 phase cells was observed for TFAM knockdown tumour cell lines based on flow cytometry results, indicating TFAM knockdown led to G1/S phase arrest and attenuated cellular proliferation." (PMID 31062473, 2019). "Remarkably, all tumor cell lines significantly increased TFAM transcript levels compared with MRC-5 cells, possibly to protect and stabilize mtDNA molecules and consequently avoid their degradation." (PMID 31681589, 2019). "In this study, we identified that decreased expression of TFAM impaired the proliferation of tumour cells by inducing G1/S phase arrest and reducing the expression of E2F1, phospo‐Rb, PCNA and TK1." (PMID 31062473, 2019). "Previous studies identified that increased TFAM expression conferred tumor cells resistance to ionizing radiation." (PMID 30862036, 2019). "Mitochondrial transcription factor A (TFAM) regulates mitochondrial biogenesis, and it is a candidate target for sensitizing tumor during therapy." (PMID 30862036, 2019). "In this study, we aimed at investigating how TFAM affected the sensitivity of tumour cells to ionizing irradiation." (PMID 31062473, 2019). "Combined with our above results, we identified a signaling mechanism where COX-2 stimulated TFAM expression in irradiated tumor cells via DRP1-mediated mitochondrial fragmentation." (PMID 30862036, 2019). "In conclusion, our current work provides evidence to show that COX-2 contributes to the up-regulation of TFAM, which further helps tumor cells to resist ionizing radiation." (PMID 30862036, 2019). "Since COX-2 has been reported to be a pro-survival protein in a wide range of tumor cells, we next detected the expression levels of TFAM and COX-2 after γ-ray irradiation." (PMID 30862036, 2019). "TFAM deficient fibroblasts produce more H2O2 and L-lactate and are sufficient to promote tumour growth." (PMID 29967776, 2018). "Positive expression of TFAM was detected in 81.40% (70/86) of tumor samples, including 8/10 grade I, 48/61 grade II, 13/14 grade III, and 1/1 grade IV samples." (PMID 29137431, 2017). "Nevertheless, some tumor cells with higher mtDNA content than the corresponding non-tumor cells were also positive for TFAM." (PMID 29137431, 2017). "The present study evaluated matched tumor and non-tumor samples to provide a comprehensive characterization of mtDNA alterations, further disclosing a significant elevation of TFAM expression in HCC." (PMID 29137431, 2017). "In conclusion, TFAM depletion in MKN45 cells inhibits tumor progression, most probably by inducing differentiation into growth-arrested polygonal cells." (PMID 29259235, 2017). "TFAM-knockdown NSCLC H460 cells lost the ability to develop tumor masses when injected into nude mice." (PMID 26820294, 2016). "We found that TFAM expression, age, smoking status, tumor pathological grade, T stage and TNM stage were significant prognostic factors in the univariate analysis." (PMID 26820294, 2016). "Our data indicate that high TFAM protein expression is significantly correlated with tumor grade and TNM stage." (PMID 26820294, 2016).
tumor (continued). "Among the factors identified, we noticed that advanced TNM stage, large tumor burden, presence of distant metastasis, and high TFAM expression were significantly related to poor overall survival (p = 0.041, p = 0.029, p = 0.028, p = 0.042, respectively)." (PMID 27732955, 2016). "For example, Pohjoismaki6 decreased the mtDNA copy number in human tumor cells through the downregulation of TFAM in vitro, and Guo23 also found that decreased TFAM activity decreased the mtDNA copy number." (PMID 25837486, 2015). "We used TFAM shRNA and EtBr to reduce the mtDNA copy number and found that this led to the increased sensitivity of tumor cells to chemotherapeutic drugs." (PMID 25837486, 2015). "Consistent with TFAM shRNA transfection, EtBr-treated tumor cells were also more vulnerable to chemotherapeutics." (PMID 25837486, 2015). "To investigate the mechanisms underlying the decrease in tumor volume in CO2 treated mice, we examined the expression of PGC-1α and TFAM in tumor tissue using quantitative real-time PCR (qRT-PCR)." (PMID 23166610, 2012). "For example, TFAM or MTERF inhibitors could be used alongside traditional treatments to synergistically halt tumor growth and sensitize cells to therapeutic interventions." (PMID 41403952, 2025). "Altered TFAM expression has been reported in several tumor types." (PMID 41226485, 2025). "Intriguingly, TFAM over-expression group also exhibited an increase in ROS levels compared with paired TFAM stable groups in tumors, strongly suggesting that ROS level of tumor tissues may influence their chemotherapy efficiency through regulated by TFAM." (PMID 41274938, 2025). "Our group has previously reported that TFAM expression decreases with increasing tumor grade." (PMID 41226485, 2025). "Transcription factor A mitochondrial (TFAM), mitochondrial ribosomal proteins, and mitochondrial respiratory complexes I and V are a few mitochondrial proteins that are the critical drivers of tumor cell progression due to their potent role in the cell cycle." (PMID 39188055, 2024). "In addition to maintaining functionality in normal cells, TFAM also plays a crucial role in the tumor process." (PMID 38589371, 2024). "Taken together, these results demonstrated that CKIP‐1 silencing could function anti‐tumour effect on OSCC cells partially via TFAM/cGAS‐STING signalling axis." (PMID 39169452, 2024). "Immunohistochemical analysis in tumor tissues also demonstrated that the combination significantly reduced the expression of TFAM, and this reduction could be reversed when TFAM was overexpressed." (PMID 39770569, 2024). "However, when TFAM protein expression is increased, the transcription of Cyt b is restored to normal, and the proliferation of tumor cells is significantly inhibited." (PMID 39763669, 2024). "Ionizing radiation could upregulate the mRNA and protein expression of TFAM, while inhibition of TFAM could increase the radiation sensitivity of tumor cells." (PMID 35454769, 2022). "The seminal study testing the impact of removing functional mitochondria by suppression of the mitochondrial transcription factor A (TFAM) demonstrated a reduction of tumor burden, highlighting the requirement for mitochondrial metabolism and ROS in KRAS-driven tumor development." (PMID 36185202, 2022). "Based on the previous results showing that Agr could promote apoptosis in CRC cells, we hypothesized that Agr would also suppress tumor growth by blocking PGC-1α/NRF1/TFAM signaling in vivo." (PMID 36591497, 2022). "It is possible that mtDNA in cancer cells may be tightly wrapped by the increased amount of TFAM, which decreases expression of mtDNA-encoded genes related to the electron-transport chain and OXPHOS and promotes tumour cells’ use of aerobic glycolysis." (PMID 35887244, 2022).
tumor (continued). "It is suspected that the discrepant roles of TFAM in different cancers could possibly be attributed to distinct metabolic features in order to adapt to different tumour microenvironments." (PMID 34663785, 2021). "Moreover, intestinal epithelial cell-specific knockout of TFAM, a transcription factor required for replication of mitochondria DNA, drastically reduced tumor formation in APCmin/+ mouse models." (PMID 34873211, 2021). "Conversely, loss-of-function mutations of mitochondrial transcription factor A (TFAM), which participates to the replication of mitochondrial genome, are incompatible with tumor formation in vivo, while heterozygosity for TFAM is crucial for a ROS-dependent intestinal tumorigenesis." (PMID 32185131, 2020). "Otherwise, mtDNA in cancer cells may be tightly wrapped by more TFAM, which leads to a lower expression of mtDNA encoding ETC/OxPhos-related genes, thereby promoting tumor cells to use aerobic glycolysis." (PMID 32039210, 2020). "Our results showed TFAM was concomitantly up-regulated with COX-2 in irradiated tumor cells." (PMID 30862036, 2019). "The results put forward a mechanism where COX-2 stimulates TFAM expression via p38-mediated DRP1/mitochondrial fragmentation signaling in irradiated tumor cells, which may be of value in understanding how to sensitize cancer cells during radiotherapy." (PMID 30862036, 2019). "Our results confirmed this hypothesis by providing data to show that selective COX-2 inhibitor NS-398 treatment blocked the induced expression of TFAM in irradiated tumor cells." (PMID 30862036, 2019). "The results of our research put forward a mechanism for the regulation of TFAM in irradiated tumor cells, which may be considered as a candidate sensitization target in cancer radiotherapy." (PMID 30862036, 2019). "Additionally, recent studies have suggested multiple function for TFAM once this protein is present in tumor cells that lack mtDNA25,43." (PMID 30242167, 2018). "Specifically, TFAM knockdown, like ddC treatment, sequentially causes mtDNA depletion, calcium-mediated mitochondrial retrograde signaling, CFAP65 induction, and PCK1 induction, resulting in polygonalization and hypoproliferation of tumor cells." (PMID 29259235, 2017). "The expression of TFAM was not correlated with cell differentiation grade, but was associated with tumor size (P = 0.038)." (PMID 29137431, 2017). "TFAM signal was enriched in all tumor tissues with reduced mtDNA content." (PMID 29137431, 2017). "We found that TFAM knockdown resulted in significantly reduced tumor growth." (PMID 26820294, 2016). "We also found that TFAM knockdown suppressed tumor growth in vivo." (PMID 26820294, 2016). "Additionally, advanced TNM stage, large tumor burden, presence of distant metastasis, and high TFAM expression were significantly related to poor overall 5-years survival." (PMID 27732955, 2016). "TFAM protein expression was markedly increased in tumor tissues (n = 30; ***p < 0.0001)." (PMID 26820294, 2016). "Although well studied in normal cells, for instance regarding aging and neurodegeneration, diabetes and obesity, it remains unknown what roles PGC1α/TFAM play in tumour progression." (PMID 25243473, 2014). "In total, TFAM was expressed in 35 tumours (66%) and undetectable in 18 tumours (34%)." (PMID 25243473, 2014). "Within the HGSC subtype, 76% of the tumours were double-positive for PGC1α/TFAM (p<0.001)." (PMID 25243473, 2014). "From this perspective, TFAM may function as a tumor suppressor in certain cancer types." (PMID 41398603, 2025). "However, when TFAM was over-expressed, there was a substantial reduction in tumor mass." (PMID 41274938, 2025). "In addition, TFAM expression was lower in tumor tissue from KMS mice compared to that from KS mice." (PMID 40057469, 2025). "TFAM may function as a tumor promoter in some other human cancers." (PMID 41398603, 2025). "Importantly, ZNF468 exerted the tumor-promoting function via up-regulation of TFAM." (PMID 38429817, 2024).
tumor (continued). "have demonstrated that mitochondrial transcription factor A (TFAM) deficiency in DCs leads to mitochondrial DNA escape, which triggers the cGAS-STING pathway to promote DC migration, maturation, antigen presentation, and secretion of inflammatory factors and restore the anti-tumor effect of DC." (PMID 39464876, 2024). "TFAM was speculated to be a tumor suppressor in renal cell carcinoma, lung cancer, gastric cancer and head and neck cancer cell lines, but a tumor promoter in esophageal cancer and colorectal cancer cell lines." (PMID 39273403, 2024). "Gaining a deeper understanding of TFAM’s functions and regulatory mechanisms in different types of tumors may contribute to the development of novel therapeutic strategies and the prediction of tumor progression and prognosis." (PMID 38589371, 2024). "Furthermore, TFAM knockdown promotes tumor formation in an MDA-MB-231 xenograft model in mice." (PMID 38124183, 2023). "Besides the tumor growth promoting role, increased TFAM also confers resistance to ionizing radiation in several types of malignances, further supporting an inhibitory role for TFAM in tumor cell apoptosis." (PMID 33771980, 2021). "Finally, we identified that TFAM knockdown increased the NAD+/NADH ratio in tumor cells." (PMID 32093281, 2020). "However, the mechanisms on how TFAM is regulated in irradiated tumor cells remain largely known." (PMID 30862036, 2019). "Taken with our result that TFAM knockdown sensitized U-2 OS and Hep G2 to ionizing radiation, it could be inferred that the enhanced expression of TFAM was a response of tumor cells to stressed conditions, and that the inhibition of TFAM might be a way for increasing the efficacy of tumor therapy." (PMID 30862036, 2019). "However, the mechanisms on how TFAM are regulated in irradiated tumor cells remain to be explored." (PMID 30862036, 2019). "Also, due to TFAM up-regulation decreasing the sensitivity of tumor cells to radiation, and because it was concomitantly up-regulated with COX-2, we then aimed at determining whether COX-2 affected the expression of TFAM in irradiated cells." (PMID 30862036, 2019). "As shown by Balliet and colleagues, the downregulation of mitochondrial transcription factor A (TFAM) in fibroblasts is linked to Cav-1 dysregulation, with a consequent induction of oxidative stress, mitochondrial dysfunction, and aerobic glycolysis in the tumour microenvironment." (PMID 29967776, 2018). "Tumor growth trend analysis further confirmed that SIRT6 overexpression and TFAM knockdown inhibited and slowed tumor growth." (PMID 41362737, 2026). "However, in different tumor cells, the expression of TFAM may exhibit two opposing functions." (PMID 38589371, 2024). "A significant increase in the PGC-1α, TFAM, and SDH levels in the OPM-BMG tumor xenografts compared to BMG-1 confirmed an increase in mitochondrial biogenesis in OPM-BMG." (PMID 36591481, 2022). "Collectively, our data uncovered a tumour-suppressing role of TFAM and mtDNA in determining HNC oncogenicity and potentially paved the way for development of TFAM/mtDNA based scheme for HNC diagnosis." (PMID 34663785, 2021). "To detect the relationship between TFAM and tumor cell autophagy, we transfected shRNA plasmids into U-2 OS, MCF7, and Hep G2 cells to generate stable cell lines with lowered expression levels of TFAM." (PMID 32093281, 2020). "In the present study, we demonstrated that γ-irradiation up-regulated the expression of TFAM in U-2 OS, Hep G2, HeLa, and MCF7 cells, indicating that the enhanced expression of TFAM is widespread in tumor cells that are exposed to ionizing irradiation." (PMID 30862036, 2019). "In this research, our results showed that p38 was activated in irradiated tumor cells and that its inhibitor repressed radiation-induced up-regulation of DRP1, as well as TFAM." (PMID 30862036, 2019). "Enhanced phosphorylation of p38 in irradiated tumor cells promoted DRP1 expression, mitochondrial fragmentation, and TFAM expression." (PMID 30862036, 2019).
tumor (continued). "In summary, all the results together indicate that the TFAM–mtDNA–calcium–CFAP65–PCK1 axis participates in the mitochondrial retrograde signaling, affecting tumor cell differentiation and proliferation." (PMID 29259235, 2017). "In the current study, we demonstrate that transcutaneous application of CO2 to human MFH cells in an engrafted tumor model, upregulated the expression of PGC-1α and TFAM, increased the number of mitochondria, and led to mitochondrial-induced apoptosis." (PMID 23166610, 2012). "They confirmed that NETs could confer a rapid tumor growth and a higher expression of PGC-1α, NRF1 and TFAM, as well as increased levels of mitochondrial density, mtDNA, ATP production and oxygen consumption rate (OCR) in cancers." (PMID 39273403, 2024). "In this regard, we observed increased levels of TFAM in stage IV tumor tissue, although it was not statistically significant." (PMID 35205159, 2022). "The protein levels of SIRT1, PGC1α, and TFAM were determined in both the tumor tissue and non-tumor tissue samples." (PMID 35205159, 2022). "In conclusion, we highlighted the prominent role of TFAM in regulating HNC malignancy and confirmed that TFAM could be a key tumour suppressor during HNC tumourigenesis." (PMID 34663785, 2021). "Our results indicated that tumour cells lacking TFAM exhibited proliferation retardation and G1/S phase cell cycle arrest." (PMID 31062473, 2019). "Although there is no report on the ultrastructure of TFAM knockdown cells, the change in morphology is similar to that reported in drug-resistant tumor cells." (PMID 29447301, 2018). "Moreover, the key mtDNA transcription factors POLRMT, TFAM, TFB1M and TFB2M were down-regulated in the GBM50 and GBM3 tumours." (PMID 30208958, 2018). "Most HCC tumor samples showed elevated expression of TFAM and depleted mtDNA content, compared to matched non-tumor specimens." (PMID 29137431, 2017). "Thus, the TFAM–mtDNA–calcium–CFAP65–PCK1 axis participates in mitochondrial retrograde signaling, affecting tumor cell differentiation and proliferation." (PMID 29259235, 2017). "Here, we found a significantly high expression of TFAM by western blotting, confirmed in 70 tumor tissues via IHC, with adjacent non-tumor cells used as negative control." (PMID 29137431, 2017). "In 81.40% of HCC samples, mitochondrial transcription factor A (TFAM) was enriched in tumor cells but not in adjacent non-tumor cells." (PMID 29137431, 2017). "Neither mtDNA depletion nor TFAM overexpression correlated with the degree of cell differentiation, though TFAM expression correlated with tumor size." (PMID 29137431, 2017). "Initial analysis of 3 tumor and non-tumor sample pairs revealed that TFAM protein levels were consistently higher in the tumor specimens (P < 0.001)." (PMID 29137431, 2017). "Furthermore, our data showed that both the TFAM mRNA and protein expression levels were significantly increased in NSCLC tumor tissues compared to adjacent normal tissues." (PMID 26820294, 2016). "In HGSC, 18 tumours were positive and three were negative for TFAM (86% and 14%, respectively) (p = 0.001)." (PMID 25243473, 2014). "Three of the four MT-CO2 negative tumours were also TFAM negative; however, there was no significant relation between expression of MT-CO2 and TFAM." (PMID 25243473, 2014).